ALCAM (activated leukocyte cell adhesion molecule)
Description:
Cell adhesion molecule that mediates both heterotypic cell-cell contacts via its interaction with CD6, as well as homotypic cell-cell contacts. Promotes T-cell activation and proliferation via its interactions with CD6. Contributes to the formation and maturation of the immunological synapse via its interactions with CD6. Mediates homotypic interactions with cells that express ALCAM. Acts as a ligand for the LILRB4 receptor, enhancing LILRB4-mediated inhibition of T cell proliferation. Required for normal hematopoietic stem cell engraftment in the bone marrow. Mediates attachment of dendritic cells onto endothelial cells via homotypic interaction. Inhibits endothelial cell migration and promotes endothelial tube formation via homotypic interactions. Required for normal organization of the lymph vessel network. Required for normal hematopoietic stem cell engraftment in the bone marrow. Plays a role in hematopoiesis; required for normal numbers of hematopoietic stem cells in bone marrow. Promotes in vitro osteoblast proliferation and differentiation (By similarity). Promotes neurite extension, axon growth and axon guidance; axons grow preferentially on surfaces that contain ALCAM. Mediates outgrowth and pathfinding for retinal ganglion cell axons (By similarity). [Isoform 3]: Inhibits activities of membrane-bound isoforms by competing for the same interaction partners. Inhibits cell attachment via homotypic interactions. Promotes endothelial cell migration. Inhibits endothelial cell tube formation.
Synonyms: CD166; MEMD
Tractability: Antibody: UniProt places it where antibodies can reach, with high confidence; its Gene Ontology location is reachable by antibodies, with high confidence; UniProt predicts a signal peptide or a membrane-spanning region. PROTAC: ubiquitination databases record sites on it; its protein half-life has been measured. Other modalities: a drug acting on it is in phase 2 or 3 trials.
Gene: Protein-coding gene on chromosome 3 (105,366,706 to 105,576,909, forward strand). Ensembl gene ENSG00000170017.
Subcellular location: Cell membrane; Cell projection, axon; Cell projection, dendrite; Secreted (Isoform 3)
Subcellular location (Human Protein Atlas): Vesicles; Predicted to be secreted
Pathways (Reactome):
Developmental Biology: L1CAM interactions
Gene Ontology:
Molecular function: identical protein binding; protein binding; signaling receptor binding
Biological process: heterophilic cell-cell adhesion; axon extension involved in axon guidance; cell adhesion; neuron projection development; neuron projection extension; retinal ganglion cell axon guidance; signal transduction
Cellular component: extracellular exosome; extracellular region; focal adhesion; immunological synapse; plasma membrane; T cell receptor complex; axon; dendrite; external side of plasma membrane; neuronal cell body
Genetic constraint (gnomAD): Loss-of-function variants: 18 observed, 56.32 expected, observed/expected ratio (o/e) 0.32, 90% interval 0.22 to 0.47. The upper end of that interval is the gene's LOEUF score, 0.47, which puts it in group 2 of 6, group 1 being the genes least tolerant of losing a copy. Missense variants: 515 observed, 635.91 expected, observed/expected ratio (o/e) 0.81, 90% interval 0.75 to 0.87. Synonymous variants: 215 observed, 225.48 expected, observed/expected ratio (o/e) 0.95, 90% interval 0.85 to 1.07.
Homologues: Orthologues: macaque ALCAM (99% identical), chimpanzee ALCAM (97% identical), dog ALCAM (96% identical), rabbit ALCAM (95% identical), pig ALCAM (95% identical), mouse Alcam (93% identical), rat Alcam (93% identical), guinea pig ALCAM (93% identical), tropical clawed frog alcam (56% identical), zebrafish alcama (37% identical), zebrafish alcamb (36% identical). Paralogues in human: BCAM (23% identical), MCAM (22% identical), AGER (16% identical).
Diseases named in the same sentence as ALCAM in open-access papers:
ALCAM is named in the same sentence as 195 diseases in open-access papers, as found by Europe PMC text mining. Sharing a sentence is not in itself a finding about the gene and the disease. The quoted sentences say what the papers report.
breast carcinoma (66 papers, 2009 to 2025). "ALCAM is also associated with tamoxifen resistance in breast cancer cells, and ALCAM knockdown substantially enhances tamoxifen-induced cancer cell viability inhibition and apoptosis." (PMID 37701037, 2023). "The reasons underlying the contrasting connection of ALCAM and clinical outcomes in breast cancer and gastrointestinal cancer are unclear." (PMID 34680335, 2021). "In a Swedish cohort of 783 breast cancer, 2 of the ALCAM single-nucleotide polymorphisms (rs1044243 and rs115) were found to be associated with the survival of the patients." (PMID 34680335, 2021). "In a cohort of 1033 breast cancers (compared with 1116 control subjects) from a Chinese study, two single-nucleotide polymorphisms (SNPs) of the ALCAM were identified, rs6437585 (C/T) and rs11559013 (A/G)." (PMID 34680335, 2021). "ICAM-1-ICAM-1 homophilic interaction was associated with breast cancer metastatic amplification, while ALCAM-ALCAM interaction was an assistant for T cell adhering to dendritic cells." (PMID 34222020, 2021). "Contrarily, decreased ALCAM expression in breast cancer and loss of ALCAM membrane expression in ovarian cancer have been correlated with poor prognosis." (PMID 33270750, 2020). "Additional studies exploring the prognostic role of ALCAM in breast cancer dissemination have implicated over-expression of ALCAM with nodal involvement and a tendency toward increased tumor cell presence in the bone marrow." (PMID 31695844, 2019). "The first novel SNP, rs9862599, identified to be suggestively associated with breast cancer from this GWAS is located on chromosome 3q13.11 near to the 5′ end of ALCAM gene." (PMID 31757997, 2019). "The purpose of this study was to investigate epigenetic alterations of the ALCAM gene using pyrosequencing analysis and to analyze the association between the methylation of the ALCAM gene and its expression in breast cancer." (PMID 29315254, 2018). "The IHC expression of ALCAM was also associated with molecular subtype of breast cancer (p = 0.001) and showed most strong expression in Luminal A subtype." (PMID 29315254, 2018). "In agreement with our results, two recent publications looking at the correlation of ALCAM tissue expression with stage and outcome in breast cancer also reveal a loss in detectable levels of ALCAM by immunohistochemistry as tumors progress." (PMID 27894096, 2017). "Since loss of ALCAM function is a bad prognostic marker in breast cancer, we examined which factors would contribute most significantly to its expression." (PMID 25255861, 2014). "Other studies confirmed that loss of ALCAM function, due to reduced expression and/or protein mislocation is a bad prognostic marker in breast cancer." (PMID 25255861, 2014). "Decreased ALCAM expression levels were associated with aggressive behavior and poor outcome in several human tumors including breast cancer, pancreatic cancer and ovarian carcinoma." (PMID 21448288, 2011). "Activated leukocyte cell adhesion molecule (ALCAM) is implicated in the prognosis of multiple cancers with low level expression associated with metastasis and early death in breast cancer." (PMID 20929568, 2010). "While the relationships between these various deregulations of ALCAM expression remain to be verified, they all represent loss of function of ALCAM, which to date has consistently been associated with poor prognosis in breast cancer." (PMID 20929568, 2010). "ALCAM expression levels (mRNA and protein) appear to be induced by the presence of Wnt5a in breast cancer cells, an expression event that is linked to the migration of breast cancer cells." (PMID 34680335, 2021). "For example, in breast cancer reduced ALCAM transcript expression has been observed to associate with more aggressive phenotypes and poorer patient outlooks with reductions of either cytoplasmic and/or membranous ALCAM staining observed in patient tumor tissue and/or those with bone metastasis." (PMID 31695844, 2019).
breast carcinoma (continued). "Because ALCAM has been implicated in the aggressiveness of breast cancer, colorectal cancer, lung cancer, melanoma, and glioblastoma, the ALCAM/syntenin interaction might regulate cell motility through controlling adhesion strength." (PMID 31454940, 2019). "However, there are only a few studies to analyze the methylation status of the ALCAM gene, although ALCAM has been implicated in prognosis of breast cancer." (PMID 29315254, 2018). "Also, the level of ALCAM transcripts was associated with the expression of TNFα, NF-κB p50, IL-4, and intratumoral inflammation in breast cancer." (PMID 29315254, 2018). "In addition, this is one of a few studies that revealed the association between ALCAM expression and the ALCAM gene methylation in breast cancer." (PMID 29315254, 2018). "In breast cancer, instead, reduced expression of ALCAM was associated with poor prognosis." (PMID 28709442, 2017). "Indeed, another group has shown in a diagnostic study that patients with breast cancer have elevated serum levels of ALCAM." (PMID 27894096, 2017). "In various neoplasms like malignant melanoma, prostate cancer, colorectal carcinoma, bladder cancer and breast cancer as well as in oral and esophageal squamous cell cancer a pathologically altered ALCAM expression has been observed and was associated with cancer progression." (PMID 22475274, 2012). "Indeed, ALCAM has been implicated in the progression and metastasis of cutaneous melanoma, prostate carcinoma, breast cancer, colorectal carcinoma, bladder cancer, and esophageal squamous cell cancer, among others." (PMID 22745734, 2012). "The clinical relationship of membrane ALCAM loss with progression in ovarian and breast cancer may also relate to the process of ALCAM shedding by ADAM17/TACE." (PMID 21364949, 2011). "Although high ALCAM expression levels have been associated with better outcome and might be predictive for chemotherapy response in breast cancer, the underlying biological mechanism for survival benefit still remains unclear." (PMID 20736952, 2010). "Also, ALCAM is linked to the inflammatory response in breast cancer." (PMID 29315254, 2018). "Also, the level of ALCAM transcripts was associated with the inflammatory markers in breast cancer." (PMID 29315254, 2018). "Thus, loss of ALCAM may contribute to the more aggressive phenotype of breast cancer among AA women." (PMID 25255861, 2014). "Thus, reduced homotypic tumor cell adhesion may explain why low-level ALCAM is a risk factor for metastasis and early death in breast cancer." (PMID 20929568, 2010). "ALCAM has been shown to promote the adherence, proliferation, and growth of cells in multiple tumors, such as breast cancer and glioma." (PMID 40118855, 2025). "This ALCAM-targeted antibody was able to inhibit 50% of the invasion of breast cancer cells in an in vitro Matrigel invasion assay and reduce the growth rate of colorectal tumours in vivo." (PMID 36614319, 2023). "Activated leukocyte cell adhesion molecule (ALCAM) is another member of IgSF that is found to be upregulated in both endothelial cells and breast cancer cells, leading to homophilic ALCAM/ALCAM interactions." (PMID 37190188, 2023). "We also found that endogenous ALCAM (CD166) is a GAL-8 ligand in human MDA-MB-231 breast cancer cells, showing a Kd of 3.19 × 10−6 M by SPR." (PMID 37898403, 2023). "High expression of ALCAM/CD166 was associated with progression, metastasis, and response to therapy in several cancers, but lower expression in other cancers, such as breast cancer correlated with an aggressive phenotype and worse prognosis." (PMID 37685904, 2023). "Immunohistochemical analysis showed that tamoxifen resistant breast cancers have a higher ALCAM staining intensity compared with tamoxifen sensitive ones." (PMID 35689436, 2022). "ALCAM-positive cells have superior sphere-forming ability and cancer-initiating potential in prostate cancer and promote evasion of apoptosis in breast cancer." (PMID 36275816, 2022).
breast carcinoma (continued). "Praluzatamab ravtansine or CX-2009, an activated antibody-drug conjugate that targets ALCAM, is currently undergoing phase II clinical trials for the treatment of breast cancer." (PMID 36275816, 2022). "Similar to our results, they showed that knockdown of ALCAM enhanced 4‐hydroxytestosterone induced cell death in tamoxifen resistant breast cancer cell line." (PMID 35689436, 2022). "Sialylation of ALCAM influenced its adhesion to Gal-8-coated surfaces, disrupted the cell adhesion, and thus led to breast cancer growth inhibition." (PMID 36482940, 2022). "Specifically in breast cancer, high expression of ALCAM occurs in approximately 50% of patients with triple-negative cancers and around 80% in patients with estrogen receptor positive, human epidermal growth factor receptor 2 (HER2) tumors." (PMID 36275816, 2022). "ALCAM is a membranous protein and takes part in cell migration and adhesion; also, it is usually expressed in breast cancer cells." (PMID 36547538, 2022). "ALCAM expression seems to have two types of patterns in breast cancer: patients with high cytoplasmic expression develop a more invasive tumour and suffer a shortened disease-free survival." (PMID 36077593, 2022). "Extensive ALCAM expression in the plasma membrane triggers attenuated adherent ability which reinforces the motility of breast cancer cells, leading to metastasis." (PMID 36077593, 2022). "A particular group of patients, namely Saudi patients with breast cancer, were found to have markedly increased levels of soluble ALCAM compared with control." (PMID 34680335, 2021). "Knockdown of ALCAM and/or galectin-8 was found to reduce levels of the matrix adhesiveness, proliferation, cell-cell adhesion of breast cancer cells, and tumour growth in vivo." (PMID 34680335, 2021). "We found that FN1, PLAU and ALCAM were upregulated in patients with most subtypes of breast cancer compared to expression in healthy volunteers." (PMID 34641959, 2021). "Low and colleagues, in their genome-wide association studies (GWAS), discovered that 3q13.11 (ALCAM), together 21q22.12 (CLIC6-RUNX1), two novel loci, are potential susceptibility indicators in Japanese breast cancer patients." (PMID 34680335, 2021). "When evaluated in clinical datasets, overexpression of FN1, PLAU, and ALCAM was observed in patients with different subtypes of breast cancer." (PMID 34641959, 2021). "Upregulation of ALCAM in flow-stimulated breast cancer cells suggested potential roles of blood flow in promoting cancer cell adhesion to endothelial cells." (PMID 34641959, 2021). "This connection in breast cancer is further supported by findings that low levels of ALCAM also appear to facilitate bone metastasis of the patients." (PMID 34680335, 2021). "In patients with breast cancer, those with high levels of ALCAM mRNA and who received chemotherapy had a better survival rate; in contrast, those with high levels but did not receive chemotherapy had a poor survival." (PMID 34680335, 2021). "When evaluated in a clinical cohort, we observed significant increase in expression of FN1, PLAU and ALCAM in patients with most subtypes of breast cancer compared to healthy volunteers." (PMID 34641959, 2021). "We also observed upregulation of FN1, PLAU and ALCAM in patients at most stages of breast cancer compared to expression in healthy individuals." (PMID 34641959, 2021). "It has been shown that the ALCAM present on activated endothelial cells interacts with L1CAM in breast cancer cells, mediating tumour-endothelial interactions." (PMID 34680335, 2021). "From the rather wide and comprehensive studies on breast cancer, it would appear that ALCAM is a favourable prognostic factor for the patients, in clear contrast to those with colorectal and gastric cancers." (PMID 34680335, 2021). "Early work has demonstrated reduced ALCAM levels in breast cancer patients who developed skeletal metastasis." (PMID 31695844, 2019).
breast carcinoma (continued). "While expression of ALCAM protects breast cancer cells against programmed cell death, its overexpression reduces the growth and migration of the tumor cells." (PMID 31244288, 2019). "For recent years, it has been indicated that low expression of ALCAM is a poor prognostic marker in breast cancer." (PMID 29315254, 2018). "In breast cancer, most of studies described that reduced ALCAM expression indicates a more aggressive phenotype and poor prognosis, whereas several studies showed that increased ALCAM expression is associated with poor prognosis." (PMID 29315254, 2018). "In this study, we studied DNA methylation status of the ALCAM gene using pyrosequencing in breast cancer tissues." (PMID 29315254, 2018). "ALCAM expression in breast cancer is reported to correlate with ER expression, lymph node metastasis, distant metastasis, and a poor prognosis." (PMID 29765514, 2018). "Further studies are needed to clarify the relevance of the epigenetic mechanism in the regulation of the ALCAM expression and prognostic value of ALCAM in breast cancer." (PMID 29315254, 2018). "DNA microarray analysis revealed that ALCAM expression in Wnt5a-positive breast cancer cells is induced by Wnt5a." (PMID 29765514, 2018). "Among individual transcripts identified by this analysis were several genes known to be associated with the metastatic process (ALCAM, MALAT1) and EMT (SNAI1, GSC, FOXC2, SIP1) and breast cancer stem cells (CD44)." (PMID 29291741, 2018). "Meanwhile, ALCAM is involved in immune response, although the precise immunological mechanisms in breast cancer have yet to be elucidated." (PMID 29315254, 2018). "We suspect that Wnt5a expression increases the malignancy of breast cancer by increasing the migratory capacity of cancer cells through the induction of ALCAM expression." (PMID 29765514, 2018). "ALCAM (CD166) is a potential breast cancer biomarker and a therapeutic target due to its role in induction of programmed cell death, apoptosis and autophagy in breast cancer." (PMID 27911271, 2017). "The invasion and metastasis of HCC are closely related to tumor cell EMT, study has shown that the decrease in ALCAM expression was accompanied by a significant upregulation of MMP-2 expression in breast cancer." (PMID 29375378, 2017). "Even after accounting for this major confounder (basal-like subtype), ALCAM expression at intercellular tumor junctions was significantly lower among the AA women with breast cancer." (PMID 25255861, 2014). "The goal of this study was to define for the first time the role of ALCAM in the ethnic disparity of breast cancer in the US." (PMID 25255861, 2014). "ALCAM expression at intercellular tumor junctions correlates with tumor grade, ER status, PR status and triple-negative tumor status in breast cancer patients." (PMID 25255861, 2014). "We reported recently that ALCAM dominantly influences the adhesive phenotypes of breast cancer cells in the pulmonary vasculature, a process that influences metastasis to the lung." (PMID 25255861, 2014). "Recent studies measured soluble ALCAM levels (s-ALCAM) in blood serum of tumor patients, e.g. breast cancer, suggesting a potential value of s-ALCAM as a biomarker for cancer detection." (PMID 22475274, 2012). "In a prior study in breast cancer patients we analysed ALCAM expression in tumor tissues on protein and mRNA level using c-DNA microarray data and western blot analysis." (PMID 22475274, 2012). "More recently high-level ALCAM in breast cancer tissues has emerged as a predictor of good outcome among patients treated with tamoxifen and adjuvant chemotherapy." (PMID 20929568, 2010). "Alteration of adhesion molecule expression is a hallmark of several cancers, however the underlying biological mechanism for the deleterious effects of reduced ALCAM in breast cancer is poorly defined." (PMID 20929568, 2010).